RNU6-1257P (RNA, U6 small nuclear 1257, pseudogene)
Gene: Small nuclear RNA gene on chromosome 20 (24,974,171 to 24,974,280, forward strand). Ensembl gene ENSG00000207355.
Homologues: Orthologues: chimpanzee U6 (97% identical), macaque U6 (93% identical), dog U6 (71% identical). Paralogues in human: RNU6-949P (86% identical), RNU6-266P (85% identical), RNU6-1060P (85% identical), RNU6-116P (85% identical), RNU6-317P (85% identical), RNU6-1011P (84% identical), RNU6-1024P (84% identical), RNU6-1042P (84% identical), RNU6-15P (84% identical), RNU6-338P (84% identical), RNU6-345P (84% identical), RNU6-39P (84% identical), and 1283 more.